COQ9 (coenzyme Q9)
Description:
Membrane-associated protein that warps the membrane surface to access and bind aromatic isoprenes with high specificity, including ubiquinone (CoQ) isoprene intermediates and presents them directly to COQ7, therefore facilitating the COQ7-mediated hydroxylase step. Participates in the biosynthesis of coenzyme Q, also named ubiquinone, an essential lipid-soluble electron transporter for aerobic cellular respiration.
Synonyms: C16orf49; DKFZP434K046; COQ10D5
Tractability: Small molecule: a structure with a bound ligand is known. PROTAC: UniProt records ubiquitination sites on it; ubiquitination databases record sites on it; its protein half-life has been measured.
Gene: Protein-coding gene on chromosome 16 (57,447,425 to 57,461,274, forward strand). Ensembl gene ENSG00000088682.
Subcellular location: Mitochondrion
Subcellular location (Human Protein Atlas): Cytosol; Mitochondria
Pathways (Reactome):
Metabolism: Ubiquinol biosynthesis
Gene Ontology:
Molecular function: isoprenoid binding; lipid binding; protein binding; protein homodimerization activity; enzyme activator activity
Biological process: ubiquinone biosynthetic process
Cellular component: mitochondrial inner membrane; mitochondrion; ubiquinone biosynthesis complex
Genetic constraint (gnomAD): Loss-of-function variants: 31 observed, 40.43 expected, observed/expected ratio (o/e) 0.77, 90% interval 0.57 to 1.03. The upper end of that interval is the gene's LOEUF score, 1.03, which puts it in group 4 of 6, group 1 being the genes least tolerant of losing a copy. Missense variants: 399 observed, 418.14 expected, observed/expected ratio (o/e) 0.95, 90% interval 0.88 to 1.04. Synonymous variants: 153 observed, 156.51 expected, observed/expected ratio (o/e) 0.98, 90% interval 0.86 to 1.12.
Gene-disease validity (ClinGen):
ClinGen rates the evidence that COQ9 causes each of these diseases.
mitochondrial disease (autosomal recessive): Definitive.
Leigh syndrome (autosomal recessive): Limited. A progressive neurological disease defined by specific neuropathological features associating brainstem and basal ganglia lesions.
Homologues: Orthologues: chimpanzee COQ9 (98% identical), dog COQ9 (92% identical), macaque COQ9 (91% identical), mouse Coq9 (90% identical), pig COQ9 (90% identical), guinea pig COQ9 (87% identical), rat Coq9 (85% identical), tropical clawed frog coq9 (66% identical), zebrafish coq9 (57% identical), Drosophila melanogaster Coq9 (31% identical).
Diseases named in the same sentence as COQ9 in open-access papers:
COQ9 is named in the same sentence as 29 diseases in open-access papers, as found by Europe PMC text mining. Sharing a sentence is not in itself a finding about the gene and the disease. The quoted sentences say what the papers report.
Encephalopathy (5 papers, 2017 to 2025). Encephalopathy is a term that means brain disease, damage, or malfunction. "Interestingly, changes in FGF21-responsive genes such as OXCT1, the SUCL complex, PDHA1, OGDH, ACO2, IDH3B, and ETC components (MT-CO2, COQ9, UQCRQ, SDHB/D and NDUFB7) are linked to mitochondrial deficiency syndromes manifesting cardiomyopathy and encephalopathy." (PMID 40998786, 2025). "Moreover, the spectrum of symptoms of encephalopathy, intellectual disability, seizures, and muscle involvement has been described in patients with variants responsible for other primary coenzyme Q10 deficiency (COQ2, COQ4, COQ6, COQ7, COQ9) as well as in patients with COQ8A-ataxia." (PMID 36295857, 2022). "Spongiform degeneration is absent in Coq9+/+ mice before and after VA supplementation but is a histopathological feature of the encephalopathy in Coq9R239X mice." (PMID 35863266, 2022).
encephalomyopathy (4 papers, 2020 to 2023). "Mutations in COQ9 have been reported in few patients, presenting with the similar lethal neonatal phenotypes characterized by encephalomyopathy and kidney involvement, including tubulopathy." (PMID 33426503, 2020). "While the determination of pathogenic variants in COQ9 is rare, mutations in the COQ9 gene are associated with primary CoQ10 deficiency and are further associated with several disease states, predominantly encephalomyopathy and an autosomal-recessive neonatal-onset CoQ10 deficiency." (PMID 36552517, 2022).
Ataxia (2 papers, 2017 to 2022). Ataxia refers to impaired coordination of voluntary muscle movement. "It should be also emphasised that rare autosomal recessive disorder, CoQ10 deficiency (mutation in CABC1; COQ2; COQ9; PDSS1; PDSS2 genes), is frequently associated with seizures, cognitive decline, pyramidal track signs, myopathy, and prominent cerebellar ataxia." (PMID 29456787, 2017).
lactic acidosis (2 papers, 2017 to 2020). Metabolic acidosis characterized by the accumulation of lactate in the body. "Recently another patient who manifested fatal neonatal lactic acidosis and encephalopathy was diagnosed with a COQ9 deficiency due to a splice site mutation that caused skipping of exons four and five." (PMID 28736527, 2017).
Mitochondrial myopathy (2 papers, 2015 to 2019). "In contrast, in the new Coq9Q95X mouse model reported here, the lack of COQ9 protein results in decreased levels of only COQ7 and COQ5 proteins, which leads to moderate CoQ deficiency and a mild mitochondrial myopathy, especially evident in females." (PMID 25802402, 2015).
astrocytomas (1 paper, 2022). "Taken together, we have demonstrated that lower CoQ10 levels and protein levels of COQ3, COQ5, COQ6, COQ7, COQ8A, and COQ9 were associated with higher tumor grades and lower CS activity or COX II level in human astrocytomas." (PMID 35204836, 2022). "The levels of COQ3, COQ5, COQ6, COQ7, COQ8A, and COQ9, but not of COQ4, were lower in Grade IV astrocytoma tissues than in controls or low-grade (Grades I and II) astrocytomas, but PDSS2 levels were higher in astrocytoma tissues than in controls." (PMID 35204836, 2022).
Hyperglycemia (1 paper, 2025). An increased concentration of glucose in the blood. "In conclusion, we report neonatal hyperglycaemia as a presenting feature of COQ10D5 in two individuals with a homozygous loss‐of‐function variant in COQ9." (PMID 40062559, 2025). "Hyperglycemia has not been previously reported in any of the 7 (3 probands and 4 siblings) individuals with COQ10D5 caused by biallelic loss‐of‐function COQ9 variants described in the literature." (PMID 40062559, 2025).
Insulin resistance (1 paper, 2018). Increased resistance towards insulin, that is, diminished effectiveness of insulin in reducing blood glucose levels. "In the present study, we found that the protein levels, but not the corresponding levels of the mRNAs, of the CoQ biosynthetic enzymes COQ7 and COQ9 were decreased in insulin resistance." (PMID 29402381, 2018). "Similarly, siRNA knock down of the key regulatory proteins in CoQ biosynthesis that were down-regulated in insulin-resistant mouse and human adipose tissue (Coq7 or Coq9) lowered mitochondrial CoQ9 and triggered insulin resistance." (PMID 29402381, 2018).
intrauterine growth retardation (1 paper, 2025). "Biallelic loss‐of‐function variants in COQ9 cause Primary Coenzyme Q10 deficiency 5 (COQ10D5; OMIM: 614654), a multiorgan condition with features including intrauterine growth retardation (IUGR), microcephaly, neurological and cardiovascular disease, and metabolic lactic acidosis." (PMID 40062559, 2025).
Mitochondrial encephalopathy (1 paper, 2016). "Here, we have developed a LV (CCoq9WP) able to overexpress Coq9 mRNA and COQ9 protein in MEFs and mHPCs from Coq9R239X mice, an animal model of mitochondrial encephalopathy." (PMID 27341668, 2016).
nephrotic syndrome (1 paper, 2015). A collection of symptoms that include severe edema, proteinuria, and hypoalbuminemia; it is indicative of renal dysfunction. "However, it remains unclear why Pdss2kd/kd mice develop nephrotic syndrome and Coq9 mutant mice do not." (PMID 25802402, 2015).
pancreatic cancer (1 paper, 2026).
mitochondrial disease (3 papers, 2009 to 2025). "Recessive loss‐of‐function variants in COQ9 cause Coenzyme Q10 deficiency‐5, a multi‐system mitochondrial disease, with 7 cases reported." (PMID 40062559, 2025). "Since we first compiled the list of putative genes, three were identified as causing mitochondrial disease in patients (C20orf7, CoQ9 and NDUFAF3)." (PMID 19852779, 2009). "This truncated COQ9 protein may produce a dominant-negative or gain-of-function effect, as it has been reported in other mitochondrial diseases." (PMID 25802402, 2015).
myopathies (2 papers, 2017). "Deficiencies in CoQ in skeletal muscle and the resulting myopathies have been associated with mutations in a number of the CoQ biosynthetic genes such as COQ9." (PMID 29190290, 2017).
genetic diseases (1 paper, 2015). "As in other genetic diseases, the low levels of Coq9 mRNA are due to NMD because the incubation of Coq9Q95X and Coq9R239X MEFs with the NMD inhibitor cyclohexamide increased the Coq9 mRNA levels." (PMID 25802402, 2015).
COQ9 also shares sentences with these, for which no sentence is quoted: coenzyme Q10 deficiency (2 papers); Nephropathy (2); cardiomyopathy (1); cardiovascular disease (1); cerebellar ataxia (1); cognitive decline (1); developmental delay (1); hypertrophic cardiomyopathy (1); Intellectual disability (1); Leigh syndrome (1); microcephaly (1); Primary Coenzyme Q10 deficiency 5 (1); Seizure (1); tumor (1).